MIR6756 (microRNA 6756)
Synonyms: hsa-mir-6756
Gene: MicroRNA gene on chromosome 11 (119,312,950 to 119,313,012, reverse strand). Ensembl gene ENSG00000284148.
Diseases named in the same sentence as MIR6756 in open-access papers:
MIR6756 is named in the same sentence as 2 diseases in open-access papers, as found by Europe PMC text mining. Sharing a sentence is not in itself a finding about the gene and the disease.
MIR6756 shares sentences with these, for which no sentence is quoted: psychiatric disorder (1 paper); schizophrenia (1).